PIK3R3 (phosphoinositide-3-kinase regulatory subunit 3)
Diseases named in the same sentence as PIK3R3 in open-access papers (continued):
Sharing a sentence is not in itself a finding about the gene and the disease.
hyperplastic polyp (1 paper, 2021). A polyp found mainly in the stomach and colon. "Along with phosphoinositide-3-kinase regulatory subunit 3 (PIK3R3) and poly(ADP-ribose) polymerase-14 (PARP14) (among others), TRIB2 was up-regulated in sessile serrated polyps (SSA/Ps), while expressed at a lower level in both the right colon and hyperplastic polyps (HPs) samples." (PMID 34198908, 2021).
inflammatory bowel disease (1 paper, 2023). A spectrum of small and large bowel inflammatory diseases of unknown etiology. "PIK3R3(phosphoinositide-3-kinase regulatory subunit 3)has been reported to increase in Inflammatory bowel disease (IBD) patients, which indicates that PIK3R3 could be a therapeutic target for IBD." (PMID 36733527, 2023).
keloid (1 paper, 2026). An irregularly shaped, elevated mark on the skin caused by deposits of excessive amounts of collagen during wound healing. "MR indicated PIK3R3 as a causal risk factor for keloids, while ANGPTL5 showed no causal association." (PMID 41889636, 2026).
medulloblastoma (1 paper, 2010). A malignant, invasive embryonal neoplasm arising from the cerebellum. "However, mRNA transcripts for components of the PI-3 kinase enzyme complex, Pik3r3 and Pik3cb, and downstream targets of PI-3 kinase signaling, Mapk8 (Jnk) and Frap1 were up regulated 2.8, 1.9, 1.5, and 1.2-fold, respectively in Pten deficient medulloblastomas." (PMID 20520772, 2010).
meningioma (1 paper, 2012). A generally slow growing tumor attached to the dura mater. "We observed that both PI3K (PIK3R1, PIK3R3) and Akt (AKT3) genes were up-regulated in fibroblastic meningioma, and total Akt and phosphorylation Akt were also overexpressed in tumor tissues." (PMID 23285163, 2012).
metabolic syndrome (1 paper, 2025). A cluster of metabolic risk factors for CARDIOVASCULAR DISEASES and TYPE 2 DIABETES MELLITUS. "The PIK3R3-HNF4α-PPARα signaling axis has an important role in lipid metabolism in hepatocytes, and the activation of PIK3R3 reduces hepatosteatosis; thus, PIK3R3 can be regarded as a promising novel target for NAFLD and metabolic syndrome treatment." (PMID 40572705, 2025).
myeloid leukemia (1 paper, 2017). A clonal proliferation of myeloid cells and their precursors in the bone marrow, peripheral blood, and spleen. "Many of those genes inhibited by SID peptide treatment (CD44, TGFβR2, LEF1, TCF7L2, FGF2, FGF5, ID2, PIK3R3) are known as direct TGIF1 targets in myeloid leukemia or embryonic stem cells." (PMID 29179446, 2017).
myopia (1 paper, 2025). "After myopia induction for 2 and 4 weeks, the expression of PIK3R3, AKT2, BAD, BCL-2, TGF-β1, E-cadherin, COLI, MMP2, and TIMP2 was detected by qPCR." (PMID 40216914, 2025). "In contrast, the expression trend of the related molecules was reversed after 4 weeks of myopia induction (*P < 0.05, **P < 0.01, and ****P < 0.0001), suggesting that PIK3R3 and p-AKT2 may be correlated with cell survival and apoptosis." (PMID 40216914, 2025). "Further, we investigated the changes of PIK3R3, AKT2 and TGF-β1, E-cadherin, COLI, BCL-2, BAD, MMP2, and TIMP2 in the sclera of myopic guinea pigs to explore their effects on the development of myopia after 2- and 4-week myopic induction." (PMID 40216914, 2025). "Meanwhile, the Gene Ontology (GO) functional annotation analysis showed that differentially expressed genes (such as PIK3R3 and AKT2) could play a role in the occurrence and development of myopia by affecting cell survival and function as well as cell migration." (PMID 40216914, 2025).
osteosarcoma (1 paper, 2024). A usually aggressive malignant bone-forming mesenchymal neoplasm, predominantly affecting adolescents and young adults. "Four ARGs-BRMS, COL4A2, FGF2, and OGT-were used to develop an RFS-predicting model, whereas seven ARGs-CD24, FASN, MMP2, EIF2AK3, ID2, PPARG, and PIK3R3-were used to develop an OS-predicting model in patients with osteosarcoma." (PMID 38217543, 2024).
ovarian tumors (1 paper, 2022). "The expression of PIK3R3 transcripts in both ovarian tumors and ovarian metastatic tumors was significantly higher than that in normal tissues." (PMID 35761259, 2022). "Next, to determine the protein levels of PIK3R3 in ovarian tumors, we searched the HPA for immunohistochemical images of normal, serous, and endometrioid cystadenocarcinoma tissues stained with antibodies against PIK3R3." (PMID 35761259, 2022).
Parkinson disease (1 paper, 2021). A progressive degenerative disorder of the central nervous system characterized by loss of dopamine producing neurons in the substantia nigra and the presence of Lewy bodies in the substantia nigra and locus coeruleus. "LncRNA H19 regulates miR-585-3p/PIK3R3 to attenuate MPTP-induced apoptosis in Parkinson's disease." (PMID 34238324, 2021).
psoriasis (1 paper, 2022). An autoimmune condition characterized by red, well-delineated plaques with silvery scales that are usually on the extensor surfaces and scalp. "Transcription of PIK3R3 attenuates skin inflammation in mice with psoriasis, and PIK3R3 gene has been identified as a key gene regulating hair growth in mice." (PMID 36611750, 2022).
pulmonary hypertension (1 paper, 2014). Increased pressure within the pulmonary circulation due to lung or heart disorder. "Many genes are functionally related to high-altitude physiology, such as angiogenesis (RGCC), pulmonary hypertension remodeling (PLA2G12A), oxygen intake (C9ORF3), neural response (GRID1 and GRIN2B), melanin synthesis (MITF, PDGFRB and PIK3R3) and heart development (FOXS1, GAA and MYLK2)." (PMID 25270331, 2014).
renal carcinoma (1 paper, 2024). A carcinoma arising from the epithelium of the renal parenchyma or the renal pelvis. "Functionally, PIK3R3 depletion promotes renal cancer cell growth and orthotopic tumor growth while its overexpression leads to decreased tumorigenesis." (PMID 38618952, 2024). "In this study, we identified the tumor suppressive role of PIK3R3 in renal cancer by negatively regulating PI3K/AKT activation." (PMID 38618952, 2024). "On the other hand, it is unclear on how PIK3R3 may regulate PI3K signaling in renal cancer." (PMID 38618952, 2024).
Sepsis (1 paper, 2019). Sepsis is defined as life-threatening organ dysfunction caused by a dysregulated host response to infection. "The PIK3R3 gene that encodes the phosphoinositide 3 kinase regulatory subunit gamma, which is expressed in immune cells and is involved in chemoattractant-induced cell migration, has also been shown to contribute to sepsis and organ damage in critically ill patients." (PMID 31022834, 2019).
thyroid autoimmune (1 paper, 2021). "Therefore, further studies are necessary to figure out whether the variations of PTPRB, PIK3R3 and TRAF3IP3 are involved in the dysfunction of thyroid autoimmune." (PMID 33568133, 2021).
ventilator-associated pneumonia (1 paper, 2025). Serious INFLAMMATION of the LUNG in patients who required the use of PULMONARY VENTILATOR. "In ventilator-associated pneumonia (VAP), distinct gene expression profiles have been identified, showing downregulation of genes like PIK3R3, ATP2A1, PI3, ADAM8, and HCN4." (PMID 39941194, 2025).
Wilms tumor (1 paper, 2024). An embryonal neoplasm characterized by the presence of epithelial, mesenchymal, and blastema components. "Collectively, ZSTK474’s targeting of PIK3R3 induces G0/G1 phase arrest in cells by suppressing the PI3K/Akt signaling pathway, ultimately hindering the progression of nephroblastoma." (PMID 39466763, 2024). "Knock-down of PIK3R3 confirmed that ZSTK474 downregulated PIK3R3, reducing Akt phosphorylation, cyclin D and CDK4 levels and elevating P21 expression in nephroblastoma cells." (PMID 39466763, 2024).
tumor (63 papers, 2007 to 2025). "PIK3R3, also called p55PIK, is overexpressed in a variety of tumors and is associated with tumor development, metastasis, and prognosis." (PMID 37212524, 2023). "Similar to previous reports, PI3K mutations were temporally heterogeneous, where 1/5 tumor (20%) exhibited a shared mutation in a PI3K regulatory subunit PIK3R3 (HGG12)." (PMID 29084603, 2017). "However, PIK3R3 expression was higher in tumor specimens having somatic mutations in TBC1D2." (PMID 35761259, 2022). "Assessing the expression of PIK3R3 across treatment groups can provide insights into evaluating chemotherapy drug resistance and tumor migration and invasion in response to chemotherapy and combination therapies." (PMID 40343301, 2025). "Specifically, the PIK3R3 gene is up-regulated in a number of tumours, including HCC, and exerts oncogenic functions." (PMID 38528259, 2024). "Overall, PIK3R3 depletion led to increased tumorigenesis while its overexpression resulted in decreased ccRCC tumor progression." (PMID 38618952, 2024). "Expression of radial glial cell signature genes (PAX6, SOX2, FABP7) and FGFR3 was confirmed in both the radial glial/astrocyte-like and tumor cell clusters, whereas PIK3R3 and AKT1 were only expressed in the tumor cell cluster." (PMID 38609519, 2024). "Elevated expression of PIK3R3 regulatory subunits has been observed across various cancer types, playing a pivotal role in tumor advancement and cell growth." (PMID 39466763, 2024). "To examine the effect of PIK3R3 on tumor development, we orthotopically injected HKC cells with either Ctrl sgRNA or 2 PIK3R3 sgRNAs (sg3 and sg4) into the kidney capsules and monitored tumor growth over time with weekly bioluminescence imaging." (PMID 38618952, 2024). "Our results on the VHL regulation of PIK3R3 mRNA stability support our observation of decreased PIK3R3 in patients with ccRCC, which is further confirmed by our PIK3R3 IHC staining results in ccRCC tumor and normal tissues." (PMID 38618952, 2024). "Mechanistically, the VHL-m6A–regulated PIK3R3 suppresses tumor growth by restraining PI3K/AKT activity." (PMID 38618952, 2024). "PIK3R3 depletion by 2 independent sgRNAs all led to increased tumor progression over time, which also corresponded with increased tumor weights and bigger tumor size at necropsy." (PMID 38618952, 2024). "In conclusion, knockdown PIK3R3 inhibits the tumor growth of HCC by upregulating the expression of CDKN1C and downregulating the expression of SMC1A by deactivating the Akt pathway and inhibiting cell proliferation and colony formation." (PMID 37212524, 2023). "Tumor tissue was collected, and the tumor size of the PIK3R3 overexpression group was larger than the control." (PMID 37212524, 2023). "Deep mutational interaction perturbation scanning of NF2 with conformation-dependent interaction partners KDM1A, EMILIN, and PIK3R3 revealed two regions critical for NF2 tumor suppressor function." (PMID 37280085, 2023). "The xenograft models showed that circ_0021350 knockdown reduced tumor volume and weight, and this effect was inhibited by miR-1207-3p downregulation and PIK3R3 overexpression." (PMID 37644421, 2023). "It maintains the oncogenic functions of PIK3R3 by sponging miR-1207-3p, thereby promoting aggressive tumor biology in cells and aggravating GBM formation and development." (PMID 37644421, 2023). "The tumor suppressive partners comprise three highly significant binding components: MIR99AHGlncRNA/PIK3R3, miR-661/ZYG11A, and PPP2R2B/ZNF136 (Supplementary Excel Files S4 and S5)." (PMID 36289596, 2022). "Using TNM plotter, we determined the differential expression of PIK3R3 in normal, tumor, and metastatic ovarian tissues." (PMID 35761259, 2022). "The level of the PIK3R3 was elevated in the HGSOC tumor organoids and HGSOC tumor tissues compared to Fallopian tube (FT) normal organoids and FT normal tissues,respectively." (PMID 35761259, 2022).
tumor (continued). "We also checked the PIK3R3 level from HGSOC tumor organoids and HGSOC tumor tissues using public dataset (GSE124766)." (PMID 35761259, 2022). "We also showed that PIK3R3 was elevated in the HGSOC tumor organoids and tissues using public datasets." (PMID 35761259, 2022). "From immunohistochemical staining data we found that PIK3R3 expression level was increased and p21 was decreased in tumor samples in contrast to adjacent tissues." (PMID 32973127, 2020). "Then, we detected the expression levels of PIK3R3 in 40 pairs of CRC tumor tissues and adjacent normal tissues." (PMID 33317596, 2020). "The results showed that the PIK3R3 expression level in CRC tumor tissues was significantly increased compared with that in adjacent normal tissues and was negatively correlated with miR-193a-5p expression in CRC tissues (r = − 0.34, P = 0.032)." (PMID 33317596, 2020). "PIK3R3 expression was significantly higher in tumor samples than in normal epithelial tissues, while p21 expression was correspondingly lower in tumor samples than in normal epithelial tissues in 10 out of 12 pairs (83.3%)." (PMID 32973127, 2020). "The results demonstrated that Ki-67 and PIK3R3 expression levels decreased in the tumor tissues in which the expression of circRNA_0000392 was knocked down." (PMID 33317596, 2020). "Then, the expression levels of Ki-67 and PIK3R3 in the two groups of tumor tissues were evaluated by immunohistochemical staining." (PMID 33317596, 2020). "Matching analysis of immunohistochemistry (IHC) scores showed that the PIK3R3 protein level was higher and the p21 protein level was lower in tumor tissues (p < 0.001)." (PMID 32973127, 2020). "For example, miR-203 functions as a tumor metastasis suppressor through inactivating the ERBB4/PIK3R3/mTOR/S6K2 signaling pathway, and miR-203 overexpression inhibited NSCLC metastasis in vitro and in vivo." (PMID 32206066, 2020). "The PI3K pathway was mutated in 46% of the tumours, with mutations in AKT1 (5.1%), PIK3R3 (2.9%), PTEN (1.4%), PIK3CB (1.4%), PIK3CG (1.4%), PIK3CD (1.4%) and PIK3CA that tended to be mutually exclusive." (PMID 26729235, 2016). "Tumor #1, in addition to the mutations observed in Tumor #2, also harbored mutations in CBL (56.7%), PIKFIVE (21%), PIK3CA (38.2%), and PIK3R3 (25%)." (PMID 27057633, 2016). "We identified cancers that expressed elevated PIK3R3 by comparing PIK3R3 mRNA expression in the tumor samples with their expression in control tissues from the same patients." (PMID 22876838, 2012). "PIK3R3 was significantly up-regulated in cancer specimens (p < 0.05) and considered over-expressed if the probe sets measured a greater than 2-fold increase in PIK3R3 expression in the tumor sample compared to its control." (PMID 22876838, 2012). "Some genes encode proteins with functions related to signal transduction (PIK3R3, MAPK8IP1, and GATA2), and one gene encodes a protein that regulates tumor invasion and metastasis (TIMP2)." (PMID 17498291, 2007). "The functional roles of PIK3R3 in CRC, to sustain cell proliferation (and presumably tumour growth), and the mTOR pathway were both disrupted following PIK3R3 knockdown, possibly reflecting the consequences of reduced PIK3R3 levels following metformin treatment." (PMID 38893174, 2024). "Additionally, we assayed PIK3R3 expression in 21 pairs of FFPE ccRCC tumor and normal samples by IHC." (PMID 38618952, 2024).
tumor (continued). "In addition, qPCR on mRNA samples from 10 frozen ccRCC tumor and normal sample pairs revealed that the mRNA level of PIK3R3 is decreased in ccRCC tumors compared with normal samples." (PMID 38618952, 2024). "Also, the levels of PIK3R3 mRNA and protein were observably elevated in the serum and tumor tissues of HCC patients." (PMID 33407443, 2021). "Meanwhile, hsa_miR_137 could directly target with the PIK3R3 gene and inhibit its function, thereby suppressing the migration and invasion of tumor cells." (PMID 34824999, 2021). "Previous studies have shown that PIK3R3 could participate in the regulation of various biological behaviors of tumor cells, such as proliferation, cell cycle, apoptosis, cell differentiation, invasion, and metastasis." (PMID 32973127, 2020). "Lastly, they confirmed that PIK3R3 is a novel target gene of miR‐132 and miR‐132 might exert its tumor suppressive function by directly targeting the PIK3R3 and regulating the AKT/mTOR pathway." (PMID 27467251, 2016). "Interestingly, these studies have identified multiple mechanisms that contribute to PIK3R3 tumor-promotional effects." (PMID 25603314, 2015). "Also, the level of PIK3R3 protein was reduced in mice tumor tissues of the sh-circ_0061395 group." (PMID 33407443, 2021). "This requires glucose uptake and energy sources for normal cellular response to stress and tumor growth, syndrome development, vascular changes, and megalocephaly (e.g., PIK3R1; PIK3CA; PIK3CG; PIK3CD; PIK3CB; PIK3R3; PIK3R2; PIK3R5; PIK3R6)." (PMID 41010006, 2025). "Through analysis of the HPA database, we recognized remarkably higher expression levels of specific proteins, including AQP1, ITGA5, MAP3K8, PIK3R3, STC1, and TGM2, in HNSCC tumor tissues." (PMID 38688945, 2024). "Therefore, PIK3R3 may serve as a tumor inhibitory factor in ccRCC." (PMID 38618952, 2024). "Particularly, immunotherapies targeting neoantigens from oncogenic driver mutations such as CTNNB1, DDX3X, and SMARCA4 and TAAs which have possible implications in tumor progression such as NEUROG1 and PIK3R3 are attractive for a better outcome in patients." (PMID 39160595, 2024). "Conversely, we also overexpressed PIK3R3 in UMRC2 cells and observed decreased tumor progression and size as well as lung metastasis." (PMID 38618952, 2024). "In support of our conclusion, we also injected UMRC2 cells engineered with PIK3R3 overexpression subcutaneously into the flanks of NSG mice and observed decreased tumor progression and tumor size." (PMID 38618952, 2024). "Protein-coding genes with increased expression across all tumor types included E2F7, ETS1, EZH2, ID3/4, MKI67, PIK3R3, and TOP2A." (PMID 36865335, 2023). "CDKN1C, a cyclin‐dependent kinase inhibitor, was significantly upregulated by PIK3R3 knockdown, and CDKN1C siRNA rescued the impaired tumor cell growth." (PMID 37212524, 2023). "For example, lncRNA-PAGBC competitively binds to the tumor suppressive microRNAs miR-133b and miR-511 and therefore titrates miRNAs off their binding sites on SOX4 and PIK3R3, which then activates AKT/mTOR pathway in gallbladder cancer." (PMID 32123162, 2020). "It is also important to note that the Pik3r3 gene, down-regulated in the livers of NRs given PFJ in the present study, is considered an oncogene important for cell proliferation and tumour growth, as it is overexpressed in certain cancers." (PMID 27795741, 2016).